PRR23A (proline rich 23A)
Tractability: No criterion of Open Targets' tractability assessment is met for any kind of drug.
Gene: Protein-coding gene on chromosome 3 (139,003,962 to 139,006,268, reverse strand). Ensembl gene ENSG00000206260.
Subcellular location (Human Protein Atlas): Microtubules; Nucleoplasm; Cytokinetic bridge; Cytosol; Mitotic spindle; Nuclear bodies
Genetic constraint (gnomAD): Loss-of-function variants: 2 observed, 1.34 expected, observed/expected ratio (o/e) 1.49, 90% interval 0.46 to 1.92. That is too few expected variants to judge how well the gene tolerates losing a copy. Missense variants: 342 observed, 328.99 expected, observed/expected ratio (o/e) 1.04, 90% interval 0.95 to 1.14. Synonymous variants: 161 observed, 154.46 expected, observed/expected ratio (o/e) 1.04, 90% interval 0.92 to 1.19.
Homologues: Orthologues: chimpanzee PRR23A (98% identical), macaque PRR23A (88% identical), rat Prr23a1 (44% identical), rat Prr23a2 (44% identical), mouse Prr23a1 (42% identical), mouse Prr23a3 (42% identical), rat Prr23a3 (42% identical), mouse Prr23a2 (41% identical), rat Prr23d1 (36% identical), mouse Prr23a4 (23% identical). Paralogues in human: PRR23B (90% identical), PRR23C (85% identical), PRR23D1 (26% identical), PRR23D2 (26% identical), PRR23E (18% identical).
Diseases named in the same sentence as PRR23A in open-access papers:
PRR23A is named in the same sentence as 1 disease in open-access papers, as found by Europe PMC text mining. Sharing a sentence is not in itself a finding about the gene and the disease.
PRR23A shares sentences with these, for which no sentence is quoted: autism spectrum disorder (1 paper).